EGFR (epidermal growth factor receptor)
Diseases named in the same sentence as EGFR in open-access papers (continued):
Sharing a sentence is not in itself a finding about the gene and the disease.
cancer (continued). "For this reason, we calculated the binding energies of these derivatives to two cancer-related proteins, i.e., EGFR and NF-κB." (PMID 35409325, 2022). "EGFR mutations and/or overexpression have been found in a variety of human malignancies, and EGFR-targeted therapy has become a standard of care in several cancers." (PMID 35740662, 2022). "EGFR inhibitors such as erlotinib and gefitinib have been developed and applied in the clinical treatment of many other cancers." (PMID 36046036, 2022). "The surface of cancer cells is often covered with a layer of growth hormone receptor protein (such as epidermal growth factor receptor, EGFR)." (PMID 35268651, 2022). "Network analysis identified, among all the queried protein targets involved in cancer and oxidative stress, EGFR was identified as an enriched hub protein within the network that scored the highest edge count." (PMID 35421091, 2022). "Taken together, our data highlight that Avns are very promising bioactive compounds that can be further developed and exploited in cancer therapy as EGFR inhibitors." (PMID 35955669, 2022). "DZ-SIM inhibited the formation of cancer cell colonies resistant to first-generation (H1650 and H1975) and third-generation EGFR-TKIs (PC9AR), and most IC50 values were lower than 10 μmol/L." (PMID 35840984, 2022). "Musa and co-workers synthesized new chalcone derivatives as COX-2 and EGFR inhibitors based on the anti-cancer and anti-inflammatory properties of chalcones." (PMID 36558921, 2022). "EGFR overexpression plays an important role in the development of malignant tumours, such as glioblastoma, NSCLC, breast cancer, head and neck cancer, pancreatic cancer." (PMID 35702041, 2022). "Curcumin can suppress the gene expression of EGFR, and downregulate the TGF-β pathway, thus leading to inhibition of cancer-associated fibroblasts (CAF)-mediated cancer progression." (PMID 35203521, 2022). "Due to its critical regulative effects on cancer cell behaviors, EGFR has been considered a promising therapeutic target." (PMID 35653344, 2022). "Amplification in epidermal growth factor receptor (EGFR) signaling is a common cause of pronounced proliferation, survival, and metastasis in cancers and is one of the prime activators of KRAS." (PMID 35664781, 2022). "Because of its dual role in terminating or amplifying EGFR signalling, much effort has been devoted to investigating the role of endocytosis in cancer cell survival and resistance to TKI therapy." (PMID 35158954, 2022). "A preliminary mechanism study suggested that compound 3d suppressed cancer cell proliferation through the EGFR-TK pathway." (PMID 35517789, 2022). "The formulation using an active substance in the form of gemcitabine which was formulated into nanoparticles with anti-EGFR ligands (SDP-GEM/PEI-PEG-anti-EGFR) indicated an increase in the eradication of cancer cells in vitro." (PMID 36085575, 2022). "Several studies have demonstrated that EGFR is often localised within lipid rafts in cancer, including in GBM." (PMID 36497413, 2022). "And therefore, more mechanistic studies of EGFR-mediated tumors are still going on to target the receptors and their roles in cancer." (PMID 36438839, 2022). "These nanoparticles are generally internalized into the cells through an EGFR-mediated endocytosis process, resulting in the formation of lysosomes and release of encapsulated drugs for cancer treatment." (PMID 36096856, 2022). "All patients who had previously received EGFR-TKI therapy at two cancer centers in China and developed resistance to targeted therapies were included." (PMID 36081560, 2022). "Proteases are necessary for ECM remodeling and EGFR-mut cancers conserved 3 members of the MMP family." (PMID 36612014, 2022). "EGFR is over-expressed in many solid tumours and is related to cancer cell proliferation, angiogenesis and metastasis, so it has a critical role in cancer growth." (PMID 34923887, 2022).
cancer (continued). "Cancer cells exhibit high cellular TK activity and activated epidermal growth factor receptor (EGFR) signaling which are required for VACV replication." (PMID 35681776, 2022). "A novel synthetic multivalent antibody retargeted exosome (MART-Exo) expresses monoclonal antibodies specific for CD3 on T cells and epidermal growth factor receptor (EGFR) on cancer cells." (PMID 35216433, 2022). "Targeted at various cell surface receptors (including EGFR), several MNTs have already demonstrated their efficacy as an anti-cancer drug delivery system in vitro and in vivo." (PMID 36432639, 2022). "It is quite clear that the fused systems are highly effective in inhibiting EGFR activity in cancer cells." (PMID 35769445, 2022). "Epidermal growth factor receptor (EGFR), a proto‐oncogene in many types of cancers, is considered a common cancer biomarker." (PMID 35430766, 2022). "EGFR is upregulated in many types of cancers and its ectodomain is heavily N-glycosylated and its intracellular domain was shown to be a substrate for O-GlcNAc transferase." (PMID 35028012, 2022). "Treatments based on EGFR-targeting kinase inhibitors and monoclonal antibodies are extensively used in selected human cancers (including lung cancer, head and neck cancer and colorectal cancer)." (PMID 36556437, 2022). "EGFR is a member of ErbB family driving the initiation and development of multiple types of cancers." (PMID 35062949, 2022). "For instance, EGFR is one of the first identified important targets of novel antitumor agents, which co-occur "Breast" 722 times, "Cancer" 4091 times, and "Driver" 94 times." (PMID 35831792, 2022). "We looked for conditions in which the interaction between EGFR and EphA2 was increased in cancer cells and analyzed the binding site between the two receptors as a way to identify a functional role." (PMID 35668076, 2022). "In particular, we propose novel regulatory roles of HDAC6 in tumorigenesis and cancer cell survival via the regulation of EGFR/Akt pathway activation." (PMID 35110592, 2022). "In a large variety of cancers, EGFR activation and active Wnt signaling directly mediate the β-catenin/TCF/LEF transcriptional complex to induce PD-L1 expression." (PMID 36231010, 2022). "Although EGFR activation has been shown to upregulate VEGF expression in many types of cancers, the specific mechanisms involved in such upregulation remain to be elucidated." (PMID 36435833, 2022). "Oncogenic KRAS mutations are established prime promoters of NSCLC and are known to incite resistance to secondary cancer therapies and EGFR inhibitors." (PMID 36003330, 2022). "The results of this study showed that the combination of sunitinib and knocking out EGFR using CRISPR/Cas9 technology has a significant effect on attenuating cancer cell proliferation, while the effect of sunitinib on cancer cells with wild EGFR is less." (PMID 35715750, 2022). "EGFR plays an essential role in regulating cell growth, proliferation and differentiation and other physiological activities of various cancer cells, which is an important target for anti-cancer drug research." (PMID 35260020, 2022). "WTAP can also promote invasion and metastasis of cancer cells by regulating epidermal growth factor receptor (EGFR) or mRNA expression." (PMID 36171885, 2022). "All these results suggest that compounds 3l can regulate cancer cell proliferation through combination with EGFR protein, and regulate the EGFR-TK pathway." (PMID 36467103, 2022). "The main pathways correlated with 59 genes are JAK-STAT signaling pathway, EGFR tyrosine kinase inhibitor resistance and cancer pathways." (PMID 35154122, 2022). "Dysfunctional EGFR, KRAS, and mammalian/mechanistic target of rapamycin (mTOR) pathway also cause metabolic reprogramming, leading to the progression of numerous cancers, including GC." (PMID 36145507, 2022).
cancer (continued). "High concentrations of EGF (>2 ng/mL) can trigger the EGFR receptor to enter cancer cells using an unconventional clathrin-independent pathway called EGFR-NCE identified by light and electron microscopy." (PMID 35448364, 2022). "The results of this study suggest that patients with high body weight should be carefully monitored for the development of acneiform rash when receiving anti-EGFR antibody drugs as cancer drug therapy." (PMID 36045384, 2022). "Increased activation of ERBB1/EGFR as well as of the other ERBB receptors have widespread involvement in cancers including, it has recently been established, in KRAS-induced lung tumorigenesis." (PMID 35971826, 2022). "In vitro treatment of EGFR-driven cancer cells with those peptide agonists was shown to decrease PTPRJ self-association, enhance its activity on EGFR, and ultimately inhibit EGFR-driven cancer cell migration." (PMID 36452504, 2022). "As a consequence, the developed conjugates displayed targeting photodynamic activities against EGFR-overexpressing cancer cells and specificity for tumors tissues in nude mice." (PMID 35213974, 2022). "While prior research has explored the individual roles of ST6Gal-I and EGFR in cancer progression from genetic and biochemical perspectives, an understanding of how these proteins work together to impact cell mechanics remains unexplored." (PMID 35157848, 2022). "In contrast to the previous report showing the gefitinib resistance caused by low-CYLD expression in NSCLC, it was the first repot that EGFR-TKIs were indeed effective for CYLD-negative cancer patients." (PMID 36376983, 2022). "After conjugating with cetuximab, the PNDs were further used to accurately target cancer cells that overexpressed EGFR." (PMID 36451698, 2022). "Most published data suggests that TRPV1 suppresses EGFR signalling in cancer cells and, therefore, has anti-tumorigenic effects." (PMID 36497413, 2022). "EGFR overexpression and/or hyperactivation is frequently observed in human cancers including GBM and EGFR alterations are used as a prognostic marker for GBM and contribute to EGFR activation-induced drug resistance in GBM." (PMID 35309946, 2022). "It has been reported that the overactive EGFR- PI3K/AKT pathway plays a vital role in perturbing the apoptotic system of cancer cells and thus evading this process altogether and targeting these pathway proteins can induce apoptosis." (PMID 36313358, 2022). "In the second part, we discuss the generation, selection, and experimental bioactivity testing of computational hit compounds for an important cancer biological target, epidermal growth factor receptor (EGFR)." (PMID 36697952, 2022). "Gefitinib is the first generation of EGFR-TKI targeting EGFR-19del and EGFR-L858R mutations, but its efficacy in CRC is lower than that of other types of cancer." (PMID 35319011, 2022). "Mechanistically, we demonstrated that leptin drove cancer development through EGFR signaling in NPC." (PMID 35778755, 2022). "Based on the research findings, the expression of EGFR and miR-128-b in cancer tissue is expressed differently than in the healthy control tissue; also, the expression profile of miR-128-b is inversely related to the mRNA and protein levels of EGFR." (PMID 36793341, 2022). "This is supported by a positive correlation between HDAC6 and epidermal growth factor receptor (EGFR), whose signaling is involved in the regulation of cell growth and in the progression of many cancers." (PMID 36358890, 2022). "GO and KEGG analyses were used for the evaluation of various genes, such as QKI, EGFR, and RGS12 that are closely associated with the incidence of cancer." (PMID 35068348, 2022). "Compounds possessing triazole scaffold V and VI revealed remarkable in vitro cytotoxicity against different human cancer cell lines via a significant inhibition of EGFR." (PMID 35408446, 2022).
cancer (continued). "EGFR is widely expressed in nearly every cancer type, and its high expression in tumors correlates with poor patient outcome." (PMID 35903247, 2022). "The over-activation of epidermal growth factor receptor (EGFR) pathways plays a critical role in the progression of cancer cell proliferation and promotes tumorigenesis." (PMID 35668817, 2022). "Preclinical data have indicated a significant improvement and synergy in the anti-cancer drug response in TNBC when EGFR and mTOR inhibitors are combined compared with single therapeutic approaches." (PMID 36428475, 2022). "The EREG/EGFR pathway is known to play a role in cancer pathogenesis by regulating cell differentiation and growth." (PMID 35954313, 2022). "A well-studied group of receptors with relevance to cancer is the epidermal growth factor receptor (ERBB) family, for which many targeted therapies have been investigated." (PMID 35740315, 2022). "For example, the EGFR lytic-peptide potentially leaves cytotoxic effects on various groups of cancer cells which are resistant to anti-EGFR antibodies and EGFR tyrosine kinase inhibitors (TKIs)." (PMID 35717207, 2022). "These NPs preferentially accumulated in cancer cells according to the amount of EGFR expressed, with higher accumulation occurring in A431s than in A549s, though both had more accumulation in comparison to RKO cells, which lack EGFR." (PMID 35079631, 2022). "In normal cells, EGFR expression is believed to be between 40,000 and 100,000 receptors per cell, while cancer cells overexpress EGFR to the tune of more than 1,000,000 receptors per cell." (PMID 35769445, 2022). "The Epidermal Growth Factor Receptor (EGFR) gene acts in the regulation of proliferation, differentiation, division, survival, and cancer development." (PMID 35741800, 2022). "In this section, we have summarized the updates related to mechanisms of resistance, evaluation of betulinic acid as a next-generation EGFR inhibitor and approaches to tackle resistance in different cancers." (PMID 36615262, 2022). "Records of 2190 patients with EGFRm+ NSCLC cancer who were treated with EGFR-TKIs (including gefitinib, erlotinib, and afatinib) at the branches of a hospital group between 2011 and 2018 were retrospectively reviewed." (PMID 35205720, 2022). "The 7D12-decorated ELP micelles fully retained their EGFR-binding capacity and were able to selectively target EGFR-overexpressing cancer cells." (PMID 35213974, 2022). "In support of this idea, several cancer cells overexpress EGFR-stabilizing proteins, such as Sortilin, TRIB3, and USP22, which suppress EGFR degradation, and their knockdown inhibits cancer cell proliferation." (PMID 36410436, 2022). "The use of next-generation sequencing (NGS) platforms that profile large panels of cancer-relevant genes has shown that EGFR-mutant tumors often harbor additional co-occurring genetic alterations, both before and after therapy." (PMID 35579943, 2022). "Similar to cetuximab, nimotuzumab, an IgG1 isotype antibody, has been shown to be capable of exerting a detrimental effect on EGFR-expressing cancer cells by NK cell-mediated ADCC in patients with SCCHN." (PMID 36185288, 2022). "The EGFR/RhoA/PKCα/ERK signaling pathway has been previously reported to modulate cancer progression and metastasis through EMT." (PMID 35804959, 2022). "In the absence of activity in unselected HNSCC populations, there is little justification to administer EGFR TKI for the treatment of this cancer." (PMID 35158773, 2022). "This kinase is responsible of Y845 phosphorylation, which is important for the EGFR/EGFRvIII translocation to mitochondria, contributing to their integrity as much as to the survival of cancer cells." (PMID 36551529, 2022). "Then, we evaluated the induced cell viability of SW620 high EGFR-expressing cancer cell lines under three treatments, including free CPT-11, CPT-11-loaded liposome, and CPT-11-loaded DSPE-PEG2000 targeting EGFR liposome using PBS treatment cells as a control." (PMID 35918704, 2022).
cancer (continued). "For instance, the ability to predict aspects of the molecular profiles of malignant tumours, such as EGFR in non-small cell lung cancer and microsatellite instability in gastrointestinal cancers, from whole slide images has been demonstrated." (PMID 35626380, 2022). "The most important features were cancer stage, cancer size, age of diagnosis, smoking, drinking status, EGFR gene, and body mass index." (PMID 36428655, 2022). "(i) anti-TfR ADCs with low-molecular anti-cancer drugs distributed via pH-sensitive cleavable linkers and (ii) anti-TfR and anti-EGFR bispecific ADCs with low-molecular anti-cancer drugs are implementable using the current technologies." (PMID 35884906, 2022). "More specifically, the dysregulation of the lncRNA MIR31HG has been described in immune-altered environments such as cancer, modifying the cell survival by downregulating the expression of components of the Epidermal Growth Factor Receptor." (PMID 35562916, 2022). "EGFR is one of the most commonly expressed cancer cell surface antigens, thus EGFR-targeted NIR-PIT is applicable to many other types of patients with EGFR-expressing tumors." (PMID 36185287, 2022). "It has long been shown that GM3 ganglioside strongly inhibits ligand-stimulated autophosphorylation of EGFR and subsequent proliferation in EGFR-overexpressing cancer cells." (PMID 35205690, 2022). "Targeting EGFR with mAbs has been a successful strategy in different cancer subtypes, especially in NSCLC and colorectal cancer." (PMID 36358874, 2022). "As expected, prior targeted therapy, which was overwhelmingly EGFR-targeted, increased the proportion of cancers with BRAF V600E (12.6% vs. 6.5%, p = 0.019) and ERBB2 amplification (5.9% vs. 2.3%, p = 0.043)." (PMID 35621667, 2022). "The data obtained suggest that nucleic acid fragments decorated with boron clusters can be freely taken up by EGFR-overexpressing cancer cells via EGF receptor-mediated endocytosis." (PMID 36499115, 2022). "We recruited patients with brain metastasis to study the effect of EGFR-TKI on the cancer cell response." (PMID 35154464, 2022). "Next, SPION@bPEI were conjugated with Erbitux (Erb), which is an anti-EGFR antibody for targeting EGFR-overexpressing cancer cell lines." (PMID 35116215, 2022). "EGFR is necessary for optimal organ development and cell proliferation and correlates with cancer progression and sensitivity for anticancer drugs, including gefitinib, which is an EGFR-targeted tyrosine kinase inhibitor." (PMID 36410436, 2022). "In this study, we demonstrated that cancer cell-targeted NIR-PIT utilizing pan-IR700 or tra-IR700 is effective against EGFR and HER2 positive EC cells and showed in vitro and in vivo the additive effect of dual-targeted PIT against EC cells and CAFs." (PMID 36418422, 2022). "In this context, the present work proposes the synthesis of a Theranostic Nanoprobe (TP), increasing specificity for cancer cells with overexpression of the epidermal growth factor receptor (EGFR), such as the MDA-MB-468 cell line." (PMID 36678728, 2022). "Neutralizing monoclonal antibodies, such as cetuximab, and small molecule tyrosine inhibitors are used to inhibit EGFR function in cancer treatment." (PMID 35745775, 2022). "ErbB3/HER3 overexpression is associated with lung, colon, gastric, and other cancers and has been also found to be responsible for resistance to HER2, IGF1R, and EGFR inhibitors in the treatment of several types of cancers." (PMID 35938171, 2022). "Epidermal growth factor receptor tyrosine kinase inhibitor (EGFR-TKI) plays an important role in cancer therapy." (PMID 36165327, 2022). "Extensive conservation of homeobox and RNA Polymerase II genes in the EGFR-mut cancers, suggests phenotypic plasticity is promoted through epigenetic modifications." (PMID 36612014, 2022). "EGFR and/or PI3K/AKT pathway activation is associated with chemotherapeutic resistance in human cancers." (PMID 36158676, 2022).